RN7SL690P (RNA, 7SL, cytoplasmic 690, pseudogene)
Gene: Miscellaneous RNA gene on chromosome 20 (20,316,755 to 20,316,994, forward strand). Ensembl gene ENSG00000264879.
Homologues: Orthologues: macaque Metazoa_SRP (83% identical). Paralogues in human: Metazoa_SRP (84% identical), Metazoa_SRP (83% identical), RN7SL524P (83% identical), RN7SL624P (83% identical), RN7SL718P (82% identical), RN7SL440P (82% identical), Metazoa_SRP (82% identical), RN7SL525P (81% identical), RN7SL387P (80% identical), Metazoa_SRP (80% identical), Metazoa_SRP (79% identical), RN7SL602P (79% identical), and 709 more.